ARG1 (arginase 1)
Diseases named in the same sentence as ARG1 in open-access papers (continued):
Sharing a sentence is not in itself a finding about the gene and the disease.
breast cancer (continued). "Pexidartinib inhibited macrophage activity, suppressed STAT3 phosphorylation, reduced ARG1 expression, and increased lymphocyte viability, thereby enhancing the antitumor efficacy of palbociclib in HR + /HER2- breast cancer." (PMID 41986650, 2026). "In breast cancer, high-CIN tumors exhibit increasing Arg1+ macrophage infiltration, accumulation of NK cells with reduced effector function, and increased resting regulatory T cell infiltration." (PMID 40175357, 2025). "The M2 macrophages subsequently secrete immunosuppressive molecules (e.g., arginase 1 [Arg1], CD206) and metastasis-promoting factors such as matrix metalloproteinase 9 (MMP9), collectively accelerating breast cancer lung metastasis." (PMID 40564894, 2025). "Bioinformatics analysis showed that DNA‐PK and functional markers of MDSCs (iNOS, Arg1, and IDO) tended to coexist in breast cancer patients." (PMID 36373232, 2023). "To examine associations between NRP expression and macrophage phenotype, we evaluated TAMs from mice bearing EO771 mammary tumors for putative markers of inflammation (CD86, iNOS) and wound-healing (CD206, Arginase-1) by flow cytometry." (PMID 35651620, 2022). "Inhibiting arginase 1 (ARG1) expression in TAMs would enhance immune therapy including anti-PD-1 and anti-CTLA4 in breast cancer." (PMID 35281061, 2022). "The absorption of the EVs—produced by breast carcinoma cells—by neutrophils increases the expression of IL-8, VEGF, arginase 1, MMP9, and CXCR4 (CD184), which are the main markers for N2 neutrophils." (PMID 36555469, 2022). "The activity of arginase enzymes (ARG1 and ARG2), which catalyze L-arginine into ornithine and urea, is increased in the TME of multiple cancers including breast cancer." (PMID 33747948, 2021). "A clinical study has been initiated to evaluate the safety, toxicity and immune correlates of administering an Arginase-1 peptide vaccine (ARG1-18,19,20) to patients with breast cancer and other solid tumors (ClinicalTrials.gov Identifier: NCT03689192)." (PMID 33747948, 2021). "iNOS is upregulated in TAMs and is involved in L-arginine metabolism, and Arg1 and iNOS from TAM inhibited T-cell responses in murine mammary tumors." (PMID 32726950, 2020). "In breast cancer patients, L-Arg is depleted by nitric oxide synthase 2 (NOS2) and arginase 1 (ARG-1) produced by myeloid-derived suppressor cells (MDSCs)." (PMID 27246354, 2016). "Mammary tumors from MMTV-RONΔMyeloid mice, compared with controls, have increased macrophage recruitment based on F4/80+ staining, increased M1 macrophage numbers based on iNOS+ staining, and decreased M2 macrophages based on Arginase-1+ staining." (PMID 40282397, 2025). "Furthermore, the interference of STAT3 (the transfection of si-STAT3) in linc00514-OVE breast cancer cells elevated the mRNA levels of TNF-α, NOS2, and IL-6, and reduced the expression of Arg-1 at both mRNA and protein levels." (PMID 32943090, 2020). "In breast cancer model mice, MDSCs accumulate in the PMN and suppress cytotoxic CD8+ T cells and NK cells through the productions of reactive oxygen species (ROS) and arginase 1 (Arg-1)." (PMID 30792719, 2019). "Interestingly, the prototypical marker of MDSCs, ARG1, was amongst the shared genes, whereas HMGB1 is specific for monocytes derived from breast cancer patients." (PMID 25992611, 2015). "Importantly, the AhR has been demonstrated to regulate the expression of immune-regulatory markers including Arg1, IDO, IL-10, COX-2, C/EBPβ, and S100A9, which are critical factors in the pathogenesis of breast cancer." (PMID 36588678, 2022). "Here, we speculate that the immunosuppressive activity of MDSCs was induced by Arg1, rather than iNOS, through IL-13/IL-13Rα1 signaling in breast cancer lung metastasis." (PMID 35805039, 2022).
breast cancer (continued). "Meanwhile, the overexpression of linc00514 in breast cancer cells inhibited the THP-1 mRNA levels of TNF-α, NOS2, and IL-6, which are M1 polarization markers of macrophages, while it promoted the expression of Arg-1 at both mRNA and protein levels, which is a M2 polarization marker." (PMID 32943090, 2020). "Lactate-induced TAM polarization and its pro-tumorigenic effects in breast cancer has been attributed to TAM-specific extracellular signal-regulated kinase (ERK)/STAT3 activation, stimulated expression of vascular endothelial growth factor (VEGF) and arginase-1 (ARG1), and stabilization of HIF-1a." (PMID 33324565, 2020). "In addition, interaction with breast cancer cells induced MMP-9 and arginase-1." (PMID 26078009, 2015). "Whilst ARG1 was not expressed, ARG2 mRNA was found in all breast cancer cell lines." (PMID 40140975, 2025).
glioma (61 papers, 2011 to 2026). A benign or malignant brain and spinal cord tumor that arises from glial cells (astrocytes, oligodendrocytes, ependymal cells). "Markers associated with an anti-inflammatory response, such as Arg1, Mrc1 and Il4ra24, are expressed at a higher level in glioma-infiltrating cells, as compared to blood-derived cells." (PMID 32555306, 2020). "The increased Arg1 expression was associated with the immunosuppressive phenotype in microglia/macrophages in rat and mice glioma models." (PMID 29963047, 2018). "Furthermore, IL-6 induces Arg-1 expression on glioma associate macrophages, leading to T cell suppression." (PMID 36430641, 2022). "Under hypoxic conditions, acrolein produced by glioma cells inhibits neutrophil activation in vitro, induces polarization of neutrophils to the N2 phenotype, and promotes the production of ARG-1." (PMID 40342932, 2025). "In glioma-bearing brains from the vehicle-treated group, the vast majority of Arg1+ cells were Gal3+ and localized within the tumor area." (PMID 40281508, 2025). "In murine and human gliomas, both malignant cells and tumor-infiltrating myeloid cells have been found to upregulate the expression of Arg1, and the resulting changes in L-arginine metabolism are a critical mechanism contributing to immune suppression." (PMID 40684232, 2025). "We determined the impact of 7aaRGD, administered as a monotherapy or combined with PD-1 blockade, on tumor growth, GAMs accumulation and phenotypes, arginase-1 levels and neovasculature in experimental gliomas." (PMID 40281508, 2025). "Both monocytic and granulocytic subsets of MDSCs accumulate within the glioma microenvironment and inhibit T-cell proliferation via arginase-1 and reactive oxygen species (ROS), thereby facilitating tumorigenesis." (PMID 41583439, 2025). "Arginine deiminase (ADI) and arginase (Arg1) have emerged as promising agents in the therapeutic armamentarium against glioma, with demonstrated anti-glioma toxicity and a reliable safety profile in both in vitro and in vivo experiments." (PMID 39239650, 2024). "Depletion of MDSCs via low-dose 5-FU treatment increased the survival of mice with glioma driven by Arg1+ MDSCs." (PMID 38464388, 2024). "Recent research demonstrated that pegylated human recombinant ARG1 depleted arginine in glioma cells and induced cytotoxicity." (PMID 37370767, 2023). "This was further corroborated by elevated arginase-1 levels synthesized by tumor-infiltrating macrophages from mouse and human gliomas that promote the generation of polyamines and thus, T cell suppression." (PMID 35784281, 2022). "Interrogation of single-cell sequencing data from gliomas shows ARG1 and ARG2 expression in both malignant cells and microglia/macrophages in human high grade gliomas." (PMID 34504786, 2021). "The neutrophil subpopulation of leukocytes secretes arginase-1 and vascular endothelial growth factors for immunosuppression and angiogenesis in gliomas." (PMID 33747971, 2021). "To explore the antitumor potential of ARG1/2 inhibition, we analyzed bulk and single-cell RNA sequencing (scRNA-seq) data from human and murine gliomas." (PMID 34504786, 2021). "In both conditions, serum from glioma patients showed a significant increase in ARG1 activity that peaked in grade IV gliomas." (PMID 35069595, 2021). "MDSCs account for more than 40% of glioma-infiltrating immune cells and expressed IL-4Rα, inducible nitric oxide synthase (iNOS) and ARG1 to inhibit the responses of glioma-killer T lymphocytes and NK cells, causing patients poor prognosis." (PMID 34211978, 2021). "Here we demonstrate that a novel, oral ARG1/2 inhibitor, which increases L-arginine levels in the brain and restores the functionality of GAMs and NK cells, sensitizes murine gliomas to the PD-1 inhibition." (PMID 34504786, 2021).
glioma (continued). "After 17 days from glioma transplantation, the treatment with rAAV2-IL-15-infected microglia reduced the number of Arg1+ M/MΦ cells infiltrated in the tumor (a marker of pro-tumoral/anti-inflammatory M/MΦ phenotype." (PMID 34552593, 2021). "As previously reported, STAT3 regulates ARG1 in MDSCs from cancer patients, and in our study, we found that its quantity and activity are significantly increased in the blood of glioma patients, in line with a previous work." (PMID 35069595, 2021). "We found that ATRX knockout in IDH-mutant glioma led to increased infiltration by monocytic-lineage cells expressing Arg1 and Vegfa." (PMID 34763709, 2021). "In the present study, we provide the compelling evidence that OAT-1746, a novel and oral small-molecule inhibitor of ARG1/2, affects glioma-microglia interactions in vitro, accumulates in the brain and modulates the TME of murine intracranial gliomas." (PMID 34504786, 2021). "We have previously demonstrated that Arg1 mRNA is upregulated in microglia exposed to glioma during reprogramming of microglia into tumor-supportive, immunosuppressive cells." (PMID 34504786, 2021). "We thus investigated the presence of ARG1 in circulating PBMCs from glioma patients, by using confocal microscopy and flow cytometry analysis." (PMID 35069595, 2021). "In vitro characterization of PDPN+ and Pdpn knockout macrophages showed PDPN-dependent enhanced Arg1 expression, an enzyme with known pro-tumorigenic function in the tumor microenvironment, in response to the presence of glioma cells." (PMID 30972297, 2019). "We observed that PDPN-deficient macrophages show a significantly impaired transcriptional upregulation of Arg1 expression in response to three different glioma cell lines." (PMID 30972297, 2019). "Accordingly, COX2 inhibitors such as acetylsalicylic acid or celecoxib were found to prevent production of PGE2, down-regulate the expression of Arg1, and delay glioma progression." (PMID 31225500, 2019). "We report the increased Arg1 expression in murine microglia exposed to human glioma GCM, suggesting the activation of immune-suppressive phenotype in these cells." (PMID 29963047, 2018). "A recent study reported that inhibition of Arg1 with the specific inhibitor in murine gliomas leads to the improved antitumor immune response and reduced tumor size." (PMID 29963047, 2018). "Murine models of paediatric sarcomas, gliomas, and glioblastomas have been shown to induce Arginase 1+/iNOS+ MDSCs." (PMID 28969007, 2017). "In experimental gliomas, tumor infiltrating microglia and macrophages upregulate their anti-inflammatory molecular signatures; notably arginase 1 (Arg1), transforming growth factor β, matrix metalloprotease 2, and interleukin 10 (IL-10)." (PMID 29164051, 2017). "Using double immunostaining for Iba1 and Arg1 (a pro-tumorigenic phenotype marker) we demonstrated that a majority of GAMs accumulating in glioma-bearing hemispheres express Arg1, which suggests their pro-tumorigenic, immunosuppressive activation." (PMID 29242629, 2017). "Here, using transgenic mice models we have confirmed that glioma MPs (i.e. CD11b+/CD45high cells) mostly arose from circulating Gr1+ cells and expressed Arg1 (an M2 marker) shortly after trafficking into tumors." (PMID 27936099, 2016). "In the present study, we demonstrate that microglia and macrophages accumulate in GL261 experimental gliomas, adapt an anti-inflammatory “M2” phenotype, express arginase-1, IL-10 and MMPs." (PMID 21901144, 2011). "Depletion of Arg1+ MDSCs via blocking migration inhibitory factor (MIF) or through a low-dose 5-flurouracil (5-FU) regime resulted in prolonged survival in a mouse model of glioma." (PMID 38464388, 2024). "For instance, one study showed that ARG1/2 was upregulated predominantly in glioma-associated macrophages as opposed to microglia." (PMID 35784281, 2022). "Further studies are needed to determine the therapeutic effect of ARG1 inhibitors on glioma." (PMID 35898872, 2022).
glioma (continued). "Moreover, it was observed that the periphery of tumor mass of high-grade gliomas presents a minority population of GAMs that express ARG1 and CD206, typical markers for M2 polarization." (PMID 30123112, 2018). "One of most established markers of polarized microglia in glioma is Arginase 1 (Arg1)." (PMID 29963047, 2018). "In PBMCs culture, glioma-derived exosomes directly promoted IL-10 and arginase-1 production and downregulation of HLA-DR by unstimulated CD14+ monocytic cells, that displayed an immunophenotype resembling that of monocytic myeloid-derived suppressor cells (Mo-MDSCs)." (PMID 28107450, 2017). "Mounting evidence suggests that glioma-infiltrating MG/MP may promote tumor growth by facilitating immunosuppression of the tumor microenvironment through different mechanisms including Arg1 expression." (PMID 27936099, 2016). "Interestingly, untreated and Plerixafor-treated gliomas presented Arg-1+ endothelial-like tubular structures in the tumor core." (PMID 27015814, 2016). "In addition to TAMs, other leukocytes also expressed high levels of Arg1 in both mouse glioma models." (PMID 27936099, 2016). "In work by Lisi and colleagues, LPS stimulation occurred in the presence of conditioned media from C6 Glioma cells, media containing growth factors, and cytokines that could have altered the response to LPS leading to Arginase-1 expression." (PMID 26757726, 2016). "Additionally, studies suggest that exosomes containing Arginase-1 derived from reprogrammed TAMs may also facilitate glioma tumor progression." (PMID 38598023, 2024). "Furthermore, arginase 1/2 can have a direct inhibiting action on glioma invasion." (PMID 38473812, 2024). "In the GL261 glioma model, which was defined as an immunotherapy-sensitive glioma model, increased expression of M1 macrophage markers (Tnfa, Irf7, and Ifng) and decreased expression of M2 macrophage markers (Arg1, Cd206 and Cd163) were found after treatment with anti-PD1 immunotherapy." (PMID 37543576, 2023). "These GBex-educated GAMs secrete vesicles enriched with arginase-1 (ARG-1), a metabolic enzyme that further drives glioma cell propagation." (PMID 41479886, 2025). "As a result, immunosuppressive TAMs accumulate in gliomas, where they secrete IL-10, TGF-β, arginase-1, and other factors that dampen T cell responses and support tumor growth." (PMID 41583439, 2025). "Although EXO from glioma cells under normoxia condition also led to an increase in ARG-1 and CD163, the effect of EXO from glioma cells under hypoxic condition was more pronounced." (PMID 39407269, 2024). "Under certain contexts, iNOS have been shown to be the main mechanism of MDSC-mediated T cell suppression through comparing different inhibitors against iNOS, Arg1, IDO and TGF-β, for example in glioma." (PMID 38464388, 2024). "TGFB1, VEGFA, ARG1, and IL10 are secreted immunosuppressive factors in glioma, while CD70 is a glioma cell-surface immunosuppressive factor." (PMID 37891828, 2023). "Using the same secretome in glioma, circulating monocytes produce increased IL10 and arginase 1 (Arg1), decrease Human Leukocyte Antigen DR isotype (HLA-DR) expression, and thereby transform into M-MDSC-like cells." (PMID 36672697, 2023). "Compared with the control group, the expression of M2-like marker ARG1 and total TAM marker IBA1 were both upregulated in glioma allografts co-implanted with GL261-LRIG3 and TAM-shNETO2." (PMID 36639372, 2023). "Results demonstrated that, when cocultured with DHX9‐overexpressed glioma cells, macrophages exhibited decreased expression of M1 markers (IL‐1b, IL‐12b, and TNF‐α) and increased expression of M2 markers (IL‐10, CD163, and ARG1)." (PMID 36377508, 2023). "We thus measured ARG1 levels in the plasma samples obtained from 64 glioma patients (15 GII, 10 GIII and 39 GIV) and found that ARG1 levels in glioma patients were significantly higher compared to HD control." (PMID 35069595, 2021).